RAD51 (RAD51 recombinase)
Diseases named in the same sentence as RAD51 in open-access papers (continued):
Sharing a sentence is not in itself a finding about the gene and the disease.
sarcoma (8 papers, 2013 to 2025). A usually aggressive malignant neoplasm of the soft tissue or bone. "Finally, we showed functional defects in HRR in sarcoma cells that were associated with functional dependency towards PARPi and WEE1i and support the clinical use of RAD51 as a predictive biomarker for PARPi sensitivity." (PMID 39535612, 2024). "Furthermore, it has been recently demonstrated that Rad54, differently from other universal HR factors such as Rad51, is specifically involved in GT or intra/inter-chromosomal association and promotes HR between chromosomes and extra-genomic DNA in human sarcoma cell lines." (PMID 23613757, 2013). "To functionally assess HRR in sarcoma cell models ex vivo, we evaluated the formation of RAD51 nuclear foci after eliciting DNA damage with olaparib and trabectedin, either as monotherapy or in combination." (PMID 39535612, 2024). "Concomitantly, HRDhigh sarcoma cells lack RAD51 nuclear foci formation upon DNA damage, further evidencing defects in HRR." (PMID 36779660, 2023). "SAHA attenuated radiation-induced Rad51 and Ku80 protein expression in two sarcoma cell lines (KHOS-24OS, SAOS2)." (PMID 28489060, 2017). "We employed immunohistochemistry (IHC) to measure PARP1, BRCA1, and RAD51 expression in a panel of 54 patient-derived sarcoma specimens." (PMID 28454547, 2017). "Immunohistochemistry score of intensity for PARP1, BRCA1, and RAD51 protein expression in formalin-fixed paraffin-embedded sarcoma samples." (PMID 28454547, 2017). "Overall, in this case, the non-compensated steady level of RAD51 plus abnormal RAD51D protein production due to its splicing variant might have transformed the tissue phenotypes into a highly aggressive type of sarcoma." (PMID 34838098, 2021). "We evaluated the formation of RAD51 nuclear foci using immunofluorescence in ex vivo MFS and UPS sarcoma cell models upon trabectedin and olaparib‐induced DNA damage." (PMID 36779660, 2023). "Moreover, RAD51 expression and nuclear foci were reduced in HRDhigh UPS and MFS tissue compared with both HRDlow sarcoma patient samples." (PMID 36779660, 2023). "We show a lack of RAD51 nuclear foci formation in HRDhigh sarcoma cells suggesting defective HRR upon DNA damage together with a functional dependency toward PARPi and DNA damaging agents." (PMID 36779660, 2023). "In addition, we showed that HRDhigh UPS and MFS patient tissue have reduced RAD51 nuclear expression compared with HRDlow low grade and a BCOR‐rearranged sarcoma patient tissue." (PMID 36779660, 2023). "To determine whether G3 Pot1b−/− sarcomas utilize ALT to elongate telomeres, we used shRad51 to efficiently deplete Rad51 and then reconstituted either GFP vector or POT1bWT." (PMID 34535663, 2021). "She had no family history of RAD51-related cancers or other types of malignancies, including sarcoma." (PMID 34838098, 2021).
small cell lung carcinoma (8 papers, 2004 to 2025). Small cell lung cancer (SCLC) is a highly aggressive malignant neoplasm, accounting for 10-15% of lung cancer cases, characterized byrapid growth, and early metastasis. "Previous studies indicate that inhibiting RAD51‐mediated DNA repair in small cell lung cancer causes DNA damage accumulation, activating the cGAS‐STING pathway to promote CD8+ T‐cell infiltration and enhance PD‐1/PD‐L1 checkpoint inhibitor efficacy." (PMID 41350246, 2025). "Our findings agreed with prior studies that RAD51 levels were well correlated with resistance to etoposide in small cell lung cancer (SCLC) cells." (PMID 37798649, 2023).
soft tissue sarcoma (8 papers, 2014 to 2025). A malignant neoplasm arising from muscle tissue, adipose tissue, blood vessels, fibrous tissue, or other supportive tissues excluding the bones. "In the present study, we examined the role of AKT signaling in regulating of Rad51 turnover and cytotoxic effects of topoisomerase II inhibitor, doxorubicin (Dox) in soft tissue sarcomas (STS) and gastrointestinal stromal tumors (GIST) in vitro." (PMID 33266502, 2020). "In support of our findings, studies have shown that RAD51 overexpression contributes to chemoresistance in human soft tissue sarcoma cells and rescues radiation sensitivity in BRCA2-defective cancer cells." (PMID 31640742, 2019). "RAD51 expression is elevated in many human cancers including breast, prostate, lung and soft tissue sarcoma." (PMID 26910887, 2016). "Suppression of RAD51 sensitizes cancer cells to DNA-damaging drugs, and RAD51 overexpression contributes to chemotherapy resistance in several types of cancer including breast, prostate and human soft tissue sarcoma cells." (PMID 26910887, 2016). "In soft tissue sarcomas and gastrointestinal stromal tumors, Akt signaling inhibition decreased the RAD51 protein level by regulating protein stability, decreasing the efficacy of homology-mediated repair of DNA DSBs, and ultimately sensitizing tumor cells to doxorubicin." (PMID 35860572, 2022).
brain tumors (7 papers, 2019 to 2025). "Our data on the increase of DSBs without a corresponding increase in rad51 loading in Rad21+/−;RAS brain tumors in which ALT is prevented, suggest that the reduction of rad21 levels prevent signalling to wapl and separase for rad51 loading." (PMID 33266037, 2020). "We assessed DNA damage by measuring the level of the DNA damage marker γH2AX, and the occurrence of HR using immunofluorescence for the DSB repair protein RAD51, both combined with telomeric FISH, in RAS and rad21;RAS brain tumors." (PMID 33266037, 2020).
liver cancer (7 papers, 2021 to 2026). An epithelial or non-epithelial malignant neoplasm that arises from the liver. "In this study, by digging the ICGC and TCGA databases, we investigated the association among the Rad51 expression and clinical characteristics in patients with liver cancer." (PMID 34115569, 2021). "This study investigated the integration of the RAD51 inhibitor B02 with neutron capture therapy for liver cancer, emphasizing its sensitizing effect when combined with BA-BNCT." (PMID 40824344, 2026). "RAD51 is overexpressed in various cancers, including malignant gliomas and cancers of the liver, ovary, breast, lung, pancreas, colon, and rectum." (PMID 34575923, 2021). "This study is the first to validate the role of Rad51 in the immune microenvironment of liver cancer employing a bioinformatics approach." (PMID 34115569, 2021). "In this study, our work indicated that Rad51 has a higher expression level in liver cancer tissues in contrast to normal tissues." (PMID 34115569, 2021). "For the verification of whether Rad51 expression has an effect on patients with liver cancer, we analyzed the expression data from the TCGA database." (PMID 34115569, 2021). "The relationship of Rad51 expression level with immune infiltration in patients with liver cancer." (PMID 34115569, 2021). "Collectively, these results suggested that RAD51 may contribute to the regulation of the autophagy pathway in GM12878, HepG2, K562, and MCF-7 cells, and the expression level of the RAD51 gene could at least be used to predict outcomes for breast and liver cancer patients." (PMID 34067336, 2021).
rectal cancer (7 papers, 2015 to 2022). A primary or metastatic malignant neoplasm that affects the rectum. "Overexpression of RAD51 leads to poor survival outcomes in rectal cancer patients, which has been attributed to increased therapy resistance." (PMID 32143539, 2020). "This raises the perspective of using Rad51 inhibitors to radiosensitize rectal cancer cells, especially in the context of cancer cell resistance towards 5-FU." (PMID 25909291, 2015).
cholangiocarcinoma (6 papers, 2010 to 2025). A carcinoma that arises from the intrahepatic biliary tree (intrahepatic cholangiocarcinoma) or from the junction, or adjacent to the junction, of the right and left hepatic ducts (hilar cholangiocarcinoma). "Increased RAD51 foci have been documented in FGFR2 driven cholangiocarcinoma cells exposed to ionising radiation, and similar findings were reported in an imatinib-resistant GIST patient-derived xenograft harbouring FGFR2 TACC2." (PMID 41150770, 2025). "It has been shown that overexpression of HMGA1 confers radioresistance by transactivating RAD51 in cholangiocarcinoma." (PMID 39690136, 2024). "In this study, we provide the first evidence that HMGA1 is involved in homologous recombination repair through regulating RAD51 in cholangiocarcinoma." (PMID 34716319, 2021). "Our study identified HMGA1 as a novel transcription factor that induces RAD51 expression in cholangiocarcinoma." (PMID 34716319, 2021). "Preclinical studies in FGFR2 driven cholangiocarcinoma and breast cancer indicate that FGFR inhibitors can down regulate RAD51 and sensitise tumours to platinum salts or to poly ADP ribose polymerase inhibitors." (PMID 41150770, 2025). "We assessed proximal and distal FA pathway function in 48 cell lines derived from gastric, pancreatic, colorectal, hepatocellular and cholangiocellular carcinomas applying assays for FANCD2 monoubiquitination and FANCD2/RAD51 focus formation." (PMID 20509860, 2010). "The analysis of samples in our cohort also showed that the degree of downregulation of the miR-204 and of some of its targets (SHCBP1, CENPA, RAD51) was higher in the intrahepatic cholangiocarcinoma samples as opposed to the extrahepatic ones." (PMID 28199974, 2017).
Infertility (6 papers, 2010 to 2023). "A homozygote mutation in XRCC2, a paralog of RAD51, was identified within a consanguineous pedigree in which males presented with azoospermia and infertility." (PMID 34402903, 2022). "However, they are infertile and show a severe block in meiotic progression associated with reduced RAD51 and DMC1 focus formation." (PMID 30305635, 2018). "The BRCA2-MEILB2-BRME1 complex is required for the assembly of RAD51 and DMC1 at meiotic DSBs during spermatogenesis since deletion of any component in the complex diminishes RAD51 and DMC1 foci formation at recombination sites, causing impaired DSB repair and infertility." (PMID 34440403, 2021). "Furthermore, we identified Rad51 as a key target of miR-10a in germ cell by bioinformatics prediction and luciferase assay, which may be responsible for the infertility of the miR-10a overexpressed mice and germ cell arrested patients." (PMID 31275170, 2019). "Spermatocytes from infertile mice show decreased RAD51 focus formation, although DMC1 was not examined." (PMID 30305635, 2018).
neuroblastoma (6 papers, 2022 to 2024). Neuroblastoma (NB) is the most common solid, extracranial childhood tumor. "Complete loss of ATM suppressed the expression of DNA repair-associated molecules FANCD2 and RAD51 and induced DNA damage in neuroblastoma cells." (PMID 37020276, 2023). "BET inhibition downregulates RAD51, whose overexpression has been associated with chemoresistance in multiple cancer types, including neuroblastoma." (PMID 36227363, 2022). "In a study of 70 neuroblastoma patients, RAD51 expression was significantly increased in stage 4 tumors compared to stage 1 and stage 2 tumors and was higher in bone marrow metastasis." (PMID 37798649, 2023). "In case of RAD51, its low expression significantly correlates with better OS in neuroblastoma patients." (PMID 36293346, 2022).
chronic myeloid leukemia (5 papers, 2013 to 2022). "Elevated RAD51 expression and enhanced HR rates have been observed in many types of cancers, including chronic myelogenous leukemia (CML), in correlation to high proliferation rate and radio- and chemo-resistance." (PMID 23341130, 2013). "IBR2 is a recognized Rad51 inhibitor to impair Rad51 multimerization and promote proteasome-mediated degradation of Rad51 protein to therefore reduce HRR function, which ultimately enhances apoptosis and impairs tumor growth of chronic myeloid leukemia." (PMID 35875146, 2022).
colorectal adenocarcinoma (5 papers, 2010 to 2022). The most common type of colorectal carcinoma. "Similarly, an increased expression of Rad51 protein in response to ETO was recently reported in colorectal adenocarcinoma cell lines." (PMID 20824055, 2010). "It has been reported that Overexpression of RAD51 is a negative prognostic marker for colorectal adenocarcinoma." (PMID 28486948, 2017).
thyroid cancer (5 papers, 2018 to 2025). "Studies have been conducted in several populations analyzing the association of RAD51 gene polymorphisms (rs11852786, rs963917, rs1801321, rs304267, rs304270, and rs1801320) with the risk of thyroid cancer." (PMID 38892180, 2024). "In general, abnormal proliferation of local tissue cells under the action of various oncogenic factors is inhibited in the presence of Rad51 mutation, reducing the risk of thyroid cancer." (PMID 34215272, 2021). "Moreover, it was discovered that the interaction of allele variants of the XRCC3 rs861539 and RAD51 rs1801321 genes may significantly influence the risk of developing thyroid cancer, depending on the histological subtype of the tumor." (PMID 38892180, 2024). "A study of a Chinese ethnic population evaluated the association of SNPs in the 3′-UTR double-strand break repair genes RAD51, RAD51B, BRCA1 (rs12516, rs8176318), BRCA2 (rs15869), XRCC4, and XRCC5 with the risk of thyroid cancer in 206 patients with PTC." (PMID 40361383, 2025). "For example, in thyroid carcinoma (THCA), 33 out of 128 (25.7%) patients in the RAD51 high group were predicted to respond to ICB treatment, while 42 out of 128 (32.8%) patients in the RAD51 low group were predicted to respond to ICB treatment." (PMID 35359409, 2022). "Although Rad51 gene mutation was found in cancer-free patients, no mutation was detected in the PTMC group, indicating that mutation of the Rad51 gene may reduce the risk of thyroid cancer." (PMID 34215272, 2021).
breast invasive carcinoma (4 papers, 2016 to 2022). "Rad51, NEIL3 and BLM, which were linked to invasive breast cancer and BRIP1 that was associated with IDC and LC, are the only genes to our knowledge that were previously linked to invasive breast carcinoma." (PMID 33662042, 2021). "In breast invasive carcinoma (BRCA) and liver hepatocellular carcinoma (LIHC), patients showing higher expression of the RAD51 gene showed significantly poor prognoses, as compared to the other group." (PMID 34067336, 2021). "Results showed that in breast invasive carcinoma (BRCA) and colon adenocarcinoma (COAD), the chemotherapy responder group expressed lower RAD51 than the non-responder group respectively." (PMID 35359409, 2022).
HIV-1 infection (4 papers, 2014 to 2025). The type species of lentivirus and the etiologic agent of acquired immunodeficiency syndrome (AIDS). "In HIV-1 infection, RAD51 expression is elevated by viral proteins like Tat and Vpr, promoting DNA repair and enhancing viral transcription through interactions with NF-κB, thereby supporting viral persistence." (PMID 41420694, 2025). "Here we demonstrate that the interplay between Rad51, a key regulator of the homologous recombination pathway of DNA repair and whose level is induced upon HIV-1 infection, with the NF-κB pathway, augments transcription of the viral promoter." (PMID 24847939, 2014). "The importance of Rad51 in HIV infection is indicated by our results with HIV-1 infection of PBMCs and the Rad51 inhibitor RI-1, which significantly decreased infection with no toxic effects on viability." (PMID 24847939, 2014). "Treatment of peripheral blood mononuclear cells with small molecules that inhibit Rad51 activity results in greater than 50% decrease in the HIV-1 infection of cells." (PMID 24847939, 2014). "The mechanism of the induction of Rad51 by HIV-1 infection is unknown but we have found that expression of HIV-1 Tat elevates Rad51 protein levels resulting in increased repair of DNA double-strand breaks via homologous recombination." (PMID 24847939, 2014). "Our earlier studies suggest that HIV-1 infection of microglia leads to the induction of Rad51." (PMID 24847939, 2014). "The interplay between HIV-1 and Rad51 that we have described may have a role in regulating latent provirus in viral reservoirs and may also be an important positive feedback mechanism during active viral replication since we report here that HIV-1 infection reciprocally induces Rad51 levels." (PMID 24847939, 2014). "In other experiments, we have also found that Rad51 is able to bind and activate NF-κB p65 in HIV-1-infected human microglial cells and interplay of Rad51 with the NF-κB signaling pathway stimulates HIV-1 gene expression while inhibition of Rad51 function represses HIV-1 infection." (PMID 25310191, 2014). "Interestingly, the level of Rad51 was not induced or even slightly reduced by HIV-1 infection in these cells in the absence of Rad51 expression plasmid or siRNA transfection (compare 2A, lane 1 to lane 5 and 2B, lane 1 to lane 5)." (PMID 24847939, 2014).
male infertility (4 papers, 2019 to 2025). The inability of the male to effect fertilization of an ovum after a specified period of unprotected intercourse. "Overexpression of miR-10a in human and mouse testicular germ cells can target and inhibit the expression of Rad51 gene, leading to meiotic arrest and complete male infertility." (PMID 40230794, 2025). "Overexpression of miR-10a in testicular germ cells of humans and mice can target and inhibit Rad51 gene expression, leading to meiotic arrest and complete male infertility." (PMID 40230794, 2025). "Knockout of Meiok21 decreases the numbers of HSF2BP and DMC1/RAD51 foci, disrupting DSB repair, synapsis and crossover recombination and finally causing male infertility." (PMID 32463460, 2020). "In sum, our data indicate that miR-10a is involved in spermatogenesis and male fertility in both human and mice by directly targeted Rad51, overexpressed miR-10a in germ cells may cause DSB repair failure during meiosis and thus lead to male infertility." (PMID 31275170, 2019). "The accumulation of R-loops induced by the deletion of Rnaseh1 caused transcriptional dysfunction of meiotic genes and impaired meiotic recombination by altering the recruitment of RAD51 and DMC1, resulting in male infertility." (PMID 38858601, 2024).
malignant glioma (4 papers, 2015 to 2025). A grade III or grade IV glioma arising from the central nervous system. "We showed that the RAD51 expression is frequently higher in tumor tissues as compared with normal ones and a high level of RAD51 is closely associated with an unfavorable prognosis in cancers, including malignant gliomas." (PMID 39865088, 2025).
medulloblastoma (4 papers, 2012 to 2021). A malignant, invasive embryonal neoplasm arising from the cerebellum. "Recently, a study has found that inactivation of CIT significantly reduces RAD51, a factor that helps to repair DNA damage, thus causing accumulation of DNA damage in medulloblastoma cells and finally leading to apoptosis." (PMID 34305997, 2021). "Here, we demonstrate that in the presence of ICI182,780, cisplatin-treated medulloblastoma cells show recruitment of Rad51 to the sites of damaged DNA and increase in HRR activity." (PMID 22439007, 2012). "However, in medulloblastoma, an enhanced ERβ activity has been associated with nuclear translocation of insulin receptor substrate 1 (IRS-1), which interacts with RAD51 at the sites of damaged DNA and reduces the HR function." (PMID 29498642, 2018). "We have previously reported that ERβ, which is highly expressed in medulloblastomas, translocates insulin receptor substrate 1 (IRS-1) to the nucleus, and that nuclear IRS-1 binds to Rad51 and attenuates homologous recombination directed DNA repair (HRR)." (PMID 22439007, 2012).